CD151 (CD151 molecule (Raph blood group))
Diseases named in the same sentence as CD151 in open-access papers (continued):
Sharing a sentence is not in itself a finding about the gene and the disease.
melanoma (15 papers, 2011 to 2024). A malignant, usually aggressive tumor composed of atypical, neoplastic melanocytes. "A recently described circRNA, circ_0020710, deriving from CD151 mRNA encoding an oncogenic transmembrane protein, promotes melanoma progression and contributes to melanoma immune evasion by sponging miR-370-3p and upregulating CXCL12 levels." (PMID 35159386, 2022). "In melanoma, circ_0020710, derived from CD151, was shown to have a high expression level in cancer tissues and was related to the malignant phenotype and poor prognosis of melanoma patients." (PMID 34496886, 2021). "In melanoma cell line, CD151–α3β1/α6β4 integrin complexes recruit small G proteins (Ras, Rac1, and Cdc42) to form integrin–CD151–GTPase complexes, finally leading to GTPase activation." (PMID 34540692, 2021). "Both CD151 and CD151-derived circ_0020710 have been overexpressed in melanoma tissues when compared to control samples." (PMID 34638331, 2021). "In summary, we detected a novel circRNA (circ_0020710, derived from CD151) that was overexpressed in melanoma tissues, and high level of circ_0020710 positively was correlated with the poor prognosis of melanoma patients." (PMID 32381016, 2020). "We detected 18 circRNAs derived from CD151, and among them, circ_0020710 was generally overexpressed in all of the melanoma tissues compared with paired normal tissues." (PMID 32381016, 2020). "In melanoma, it has been demonstrated that CD151 affinity interaction stimulates integrin-dependent signal transduction, resulting in increased cell migration and MMP-9 expression." (PMID 32381016, 2020). "CircRNAs derived from oncogene CD151 were detected and verified by analyzing a large number of melanoma samples through quantitative real-time polymerase chain reaction (qRT-PCR)." (PMID 32381016, 2020). "Herein, we detected the level of CD151-derived circRNAs from four paired human melanoma samples, and results showed that circ_0020710 was the most significantly overexpressed circRNAs in melanoma tissues compared with matched normal tissues." (PMID 32381016, 2020). "It is of note that expression of CD151 in the host contributes to cancer progression—CD151 knockout (KO) mice have fewer skin, melanoma, lung, and prostate cancers than their wild type (WT) counterparts." (PMID 29946318, 2018). "Tspan8 was originally identified as a tumor-associated antigen by an antibody (CO-029), CD63 by a melanoma-associated antigen (ME491), CD151 was re-identified by an antimetastatic antibody, and CD82/KAI1 as a metastasis suppressor gene." (PMID 29946318, 2018). "We have also previously shown that CD151 increases motility and invasiveness of melanoma cells by stimulating β1 integrin-mediated signaling cascades." (PMID 27926483, 2017). "In B16BL6 murine melanoma cells, interaction of CD151 with α3β1 integrin was reduced with its glycosylation, subsequently altering cell migration and invasion." (PMID 27556355, 2016). "Importantly, CD151-derived circRNA circ_0020710 was significantly overexpressed in melanoma tissues and its upregulated expression induced melanoma immune evasion." (PMID 35800365, 2022). "Moreover, we found that circ_0020710 was more resistant to RNase R than linear CD151 in two randomly selected melanoma cell lines." (PMID 32381016, 2020). "Several other tetraspanins, mainly CD9, CD81, CD82 and CD151 have been described to regulate proMMP-2 and/or proMMP-9 expression in cancer cell lines from liver, kidney, breast and lung carcinomas, fibrosarcomas and melanomas." (PMID 32455575, 2020). "In this study, we identified a novel circRNA derived from the CD151, termed circ_0020710, was significantly overexpressed in melanoma tissues compared with matched normal tissues and benign nevi tissues, and high circ_0020710 level was positively correlated with poor prognosis of melanoma patients." (PMID 32381016, 2020).
melanoma (continued). "Furthermore, it has been reported that the tetraspanin CD151, known to upregulate melanoma cell motility, was able to disturb the mode of integrin diffusion at the plasma membrane." (PMID 28188308, 2017). "However, c-Src and FAK activities were slightly reduced, presumably because CD151 is also important for their activation, as shown in melanoma cells." (PMID 25033048, 2014). "Thus, CD151, as an oncoprotein, plays an important role in tumor progression, including melanoma." (PMID 32381016, 2020). "Other tetraspanin proteins including CD63, CD73, CD151, and Tspan8 have also been shown to modulate the EMT process and tumor progression in colorectal cancer, gastric cancer, melanoma, and renal cell carcinoma." (PMID 35280793, 2022).
gastric cancer (14 papers, 2013 to 2024). A primary or metastatic malignant neoplasm involving the stomach. "Bioinformatics analysis with TCGA data indicated that CD151 mRNA level was positively correlated with FAM3C level in gastric cancer and was inversely associated with overall survival of stomach cancer patients (P = 0.024)." (PMID 37056931, 2023). "Evidences implicate that CD151 forms a complex with integrin α3 in gastric cancer cells and is positively associated with the invasiveness of gastric cancer." (PMID 34222025, 2021). "miR-152 suppresses the proliferation and motility of gastric cancer cells targeting CD151 and FGF2, which are cell surface receptors well-known to participate in the spreading, migration and invasion of tumors." (PMID 32083000, 2020). "Forced expression of miR-22 repressed proliferation, colony formation, migration and invasion of gastric cancer cells by targeting CD151." (PMID 28882183, 2017). "Given that miR-152 was reported to target CD151 expression in gastric cancer, repressing gastric cancer cell proliferation and motility, further studies will evaluate the role of this particular microRNA in regulating CD151 expression in osteosarcoma." (PMID 27556355, 2016). "Twenty HGC specimens and matched nontumor samples, human gastric epithelial cells (HGEC), and four gastric cancer cell lines were used to analyze CD151 expression." (PMID 23533596, 2013). "Taken together, our results suggest that CD151 is a positive regulator of gastric cancer metastasis." (PMID 23533596, 2013). "Notably, we revealed that integrins α6β1 and α6β4 in Edu-Neus can interact with CD151 in stomach cancer cells, which results in lymphatic tumor cell-neutrophil cluster formation and facilitates tumor invasion." (PMID 37056931, 2023). "PVT1 could increase the expression of CD151 through binding to miR-152 and inhibiting the expression of miR-152 to promote gastric cancer." (PMID 34222025, 2021). "Moreover, hsa-miR-124-3p regulates the expression of the CD151 protein by inosculation with the 5′UTR to take part in the development of gastric cancer." (PMID 30761178, 2019). "It was also reported that PVT1 activates CD151 and FGF2 expression through suppression of miR-152 in gastric cancer." (PMID 36624401, 2023). "Together, TSPAN8, CD151, TSPAN1, and TSPAN4 are overexpressed in gastric cancer tissues and are related to a higher clinical stage and poorer prognosis via interacting with other molecules in TEMs." (PMID 34222025, 2021). "Here, we summarize tetraspanins that enhance the proliferation and invasion of gastric cancer cells, including TSPAN8, CD151, TSPAN1, and TSPAN4." (PMID 34222025, 2021). "In good agreement, PVT1 is negatively correlated with miR-152 expression in tumors from gastric cancer patients, and its genetic manipulation in SGC7901 and BGC823 gastric cell lines influences miR-152 levels and ultimately, CD151 and FGF2 expression." (PMID 32083000, 2020). "However, the role of CD151 in human gastric cancer (HGC) remains unclear." (PMID 23533596, 2013). "In general, the expression of TSPAN8, CD151, TSPAN1, and TSPAN4 is increased in gastric cancer tissues and enhance the proliferation and invasion of gastric cancer cells, while CD81, CD82, TSPAN5, TSPAN9, and TSPAN21 are downregulated and suppress gastric cancer cell growth." (PMID 34222025, 2021).
prostate carcinoma (14 papers, 2010 to 2024). A carcinoma that arises from epithelial cells of the prostate gland. "Unexpectedly, several recent studies have implicated CD151 as a suppressor of tumor metastasis, particularly in ovarian and prostate cancers." (PMID 33919420, 2021). "In addition, our review will be concentrated on the evolving role of CD151 and associated protein complexes in breast, ovarian and prostate cancers, and glioblastoma, as well as their potential for clinical application." (PMID 33919420, 2021). "In prostate cancer cells, CD151 is associated with increased invasiveness and lymphangiogenesis." (PMID 27556355, 2016). "Furthermore, elevated CD151 expression was previously linked to poor prognosis in human lung and prostate cancers." (PMID 27556355, 2016). "The novel complex was tested against prostate cancer stem cells, tumorspheres, formed from surface marker CD151-positive and CD151-negative phenotypes of DU145 cells." (PMID 38410816, 2024). "CD151 has been shown to mediate communication between PC3 prostate cancer cells and the bone environment and promoted the migration and invasion of the tumours." (PMID 35685372, 2022). "During the research, two proteins contained in medium extracellular vesicles showing extraordinary specificity were identified: CDCP1 and CD151, in the context of prostate cancer." (PMID 36359374, 2022). "Because of the strong clinical implications, here we will discuss this twist by centering around recent studies of CD151 function in solid tumors, particularly breast and prostate carcinomas." (PMID 33919420, 2021). "EVs are enriched in tetraspanins, two of which (CD9 and CD151) have altered expression patterns in many solid tumours, including prostate cancer, as they advance toward metastasis." (PMID 29891991, 2018). "A similar scenario can be said for the so-called integrin-free CD151 in prostate cancer cells." (PMID 33919420, 2021). "In fact, the current view of the pro-metastatic role of CD151 in prostate cancer was largely drawn from studies with the endocrine subtype-related Tramp model, and analyses with the PC-3 cell line which is regarded as oncogene-targeting squamous epithelial cells." (PMID 33919420, 2021). "In this context, the tumor-suppressive role of integrin-free CD151 in prostate cancer may be regarded as recruiting the PKC-like signaling molecules to strengthen cell-cell adhesion through oligomerized CD151 molecules." (PMID 33919420, 2021). "The prognostic value of CD151 was previously emphasized in low-grade prostate cancer, in which CD151 expression could predict the clinical outcome of patients more accurately than the traditional histological grading method." (PMID 32117989, 2020). "A correlation between nonintegrin-associated CD151 (NIA-CD151) and diminished prostate cancer patient survival underscores the potential importance of NIA-CD151." (PMID 30778617, 2019). "Furthermore, CD151 has been shown to be a better predictor of prognosis in patients with prostate cancer than histological grading." (PMID 23533596, 2013). "In prostate cancer, the altered expression of the tetraspanins CD9 and CD151 is commonly seen as a tumour progresses towards a metastatic phenotype." (PMID 29891991, 2018). "A recent study also identified a subset of tumor-initiating stem-like cells in human prostate cancer cell lines and xenografts based on co-expression of the human pluripotent stem cell marker TRA-1-60, CD151 and CD166." (PMID 22880034, 2012). "Typically, when prostate cancers become more aggressive and progress towards a metastatic phenotype, they experience alterations in tetraspanin expression, where CD9 levels decrease and CD151 levels increase." (PMID 29891991, 2018).
non-small cell lung carcinoma (10 papers, 2003 to 2023). A group of at least three distinct histological types of lung cancer, including non-small cell squamous cell carcinoma, adenocarcinoma, and large cell carcinoma. "Overexpression of CD151 has been detected in many tumor types, and increased CD151 expression has been associated with a poor prognosis in breast, pancreatic, and non-small-cell lung cancers as well as HCC." (PMID 23533596, 2013). "On the other hand, overexpression of TSPAN24 (CD151) was detected in breast, pancreatic, colorectal, and non-small-cell lung cancer (NSCLC) and predicted poor prognosis." (PMID 29650964, 2018). "CD151 overexpression often predicts unfavorable outcome in many cancer, such as gastric, prostate and non-small cell lung cancer." (PMID 27888619, 2017). "Meanwhile, CD151 could promote non-small cell lung cancer cell proliferation, migration, and invasion by interacting with integrin α3β1 to enhance EGFR signaling." (PMID 36941633, 2023). "In lung cancer where invasive methods like transbronchial needle aspiration or transthoracic biopsy are used as the diagnosis methods, sEV markers like CD151, CD171, and tetraspanin 8 were identified as a combined diagnostic marker in 276 Non-small cell lung carcinoma (NSCLC) patients." (PMID 36612209, 2022). "Moreover, CD151 enhances cell motility and cancer metastasis and CD151 overexpression leads to a poor prognosis of the patients with non-small cell lung cancer." (PMID 12838318, 2003). "However, the precise function of CD151 in non-small cell lung cancer (NSCLC) remains unclear." (PMID 34108040, 2021). "CD151, CD171, and tetraspanin 8 were highly expressed in Non-Small Cells Lung Cancer (NSCLC) patients exosomes with respect to healthy donors, representing a powerful biomarker of tumor burden." (PMID 32759810, 2020). "Examination of exosomes from plasma of 276 non-small cell lung cancer (NSCLC) patients shows, that CD151, CD171, and tetraspanin 8 are the strongest separators of patients with LC of all histological subtypes." (PMID 33207614, 2020). "Previous studies in patients with non-small cell lung cancer have shown that proteins commonly used to screen tumor biomarkers can be used as exosome biomarkers of non-small cell lung cancer, such as EGFR, CD151, CD171, tetraspanin 8, and NY-ESO-1." (PMID 30733650, 2019).
viral infection (10 papers, 2007 to 2025). "CD151 was previously implicated in several viral infections including papillomavirus, cytomegalovirus and human immunodeficiency virus." (PMID 32117989, 2020). "In previous studies, on drug treatment before viral infection, natural plant compounds reduced the adsorption and invasion of PRRSV-susceptible cells by altering the expression of receptors, such as CD163 and CD151." (PMID 39228381, 2024). "These potential mechanisms include NF-kB-mediated immune response (i.e. PIDD1), immune synaptic interaction involved in T cell activation (i.e. CD151) and T cell exhaustion in viral infection (i.e. CD244)." (PMID 34027315, 2021). "The novel action of CD151 on viral nuclear export signaling associated with H3N2 and H1N1 infection highlights the potential of CD151 to be developed as a novel therapy to treat influenza and other viral infections." (PMID 32117989, 2020). "The viral infectivity assays performed with cd151-dsRNA treatment, antibodies against the CD151 protein, or upon GW4869 treatment showed reduced viral infections." (PMID 40806523, 2025). "It seems that the putative PRRSV receptors, CD151, integrin and vimentin, primarily expressed on PGE mediates viral infection and cellular responses at the early infection." (PMID 37099541, 2023). "To investigate possible changes of CD151 clusters during virus infection, we treated HaCaT cells with PsVs for 5 hr and analyzed by STED microscopy the immunostaining pattern of CD151 on membrane sheets generated prior to fixation." (PMID 31107240, 2019). "This is in line with previous studies demonstrating that CD63 and CD151 are involved in HPV and HCMV infection and that the C-terminal domains of these tetraspanins are indispensable for their role in virus infection." (PMID 30279342, 2018). "How can CD151, a transmembarane protein, by virtue of its binding to PRRSV RNA help in virus infection?" (PMID 17572908, 2007). "CD151, an important member of tetraspanin superfamily, has shown to play a significant role in the viral penetration of human cytomegalovirus (CMV) and aids in the nuclear export signaling of human influenza virus, thus suggesting a novel role for this molecule in viral infections." (PMID 40806523, 2025).